IL20RB (interleukin 20 receptor subunit beta)
Description:
The IL20RA/IL20RB dimer is a receptor for IL19, IL20 and IL24. The IL22RA1/IL20RB dimer is a receptor for IL20 and IL24.
Synonyms: IL-20R-beta; IL-20RB; FNDC6; DIRS1; IL-20R2; MGC34923
Tractability: Antibody: its Gene Ontology location is reachable by antibodies, with high confidence; UniProt predicts a signal peptide or a membrane-spanning region. PROTAC: ubiquitination databases record sites on it.
Gene: Protein-coding gene on chromosome 3 (136,946,230 to 137,011,085, forward strand). Ensembl gene ENSG00000174564.
Subcellular location: Membrane
Subcellular location (Human Protein Atlas): Vesicles; Cytosol
Pathways (Reactome):
Immune System: Interleukin-20 family signaling
Gene Ontology:
Molecular function: cytokine receptor activity; protein binding; interleukin-20 binding
Biological process: interleukin-19-mediated signaling pathway; apoptotic process; cellular response to interleukin-4; cytokine-mediated signaling pathway; dendritic cell differentiation; negative regulation of type II interferon production; osteoclast differentiation; positive regulation of interleukin-13 production; positive regulation of interleukin-4 production; regulation of cell population proliferation
Cellular component: interleukin-20 receptor complex; receptor complex; plasma membrane; membrane
Genetic constraint (gnomAD): Loss-of-function variants: 20 observed, 29.14 expected, observed/expected ratio (o/e) 0.69, 90% interval 0.48 to 1. The upper end of that interval is the gene's LOEUF score, 1, which puts it in group 4 of 6, group 1 being the genes least tolerant of losing a copy. Missense variants: 274 observed, 318.09 expected, observed/expected ratio (o/e) 0.86, 90% interval 0.78 to 0.95. Synonymous variants: 127 observed, 124.69 expected, observed/expected ratio (o/e) 1.02, 90% interval 0.88 to 1.18.
Homologues: Orthologues: chimpanzee IL20RB (99% identical), macaque IL20RB (99% identical), dog IL20RB (83% identical), guinea pig IL20RB (79% identical), mouse Il20rb (77% identical), pig IL20RB (75% identical), rabbit IL20RB (73% identical), rat Il20rb (72% identical), tropical clawed frog il20rb (31% identical). Paralogues in human: IFNGR2 (21% identical), IL20RA (19% identical), IL10RB (17% identical), IFNAR1 (17% identical), IFNGR1 (17% identical), IFNLR1 (17% identical), F3 (16% identical), IL22RA2 (15% identical), IL10RA (15% identical), IFNAR2 (14% identical), IL22RA1 (13% identical).
Diseases named in the same sentence as IL20RB in open-access papers:
IL20RB is named in the same sentence as 72 diseases in open-access papers, as found by Europe PMC text mining. Sharing a sentence is not in itself a finding about the gene and the disease. The quoted sentences say what the papers report.
lung carcinoma (10 papers, 2020 to 2024). "In the context of bone metastasis in lung cancer, the expression of IL-20RB is associated with the growth and progression of lung cancer cells within the bone." (PMID 38260135, 2023). "Tumoral expression of IL-20RB was associated with bone metastasis of lung cancer, and functionally, IL-20RB promoted metastatic growth of lung cancer cells in bone." (PMID 36006737, 2022). "IL-20RB expression is associated with bone metastasis of lung cancer." (PMID 36006737, 2022). "High expression of IL20RB was reported in lung cancer bone metastases, clear cell renal cell carcinoma and papillary renal cell carcinoma." (PMID 38098005, 2023). "Taken together, these results argue for the potential of IL-20RB targeting as a therapeutic strategy for treating lung cancer bone metastasis." (PMID 36006737, 2022). "Taken together, these data suggest that tumor cells can induce the secretion of IL-19 from osteoclasts and that osteoclast-derived IL-19 in turn facilitates the proliferation of IL20RB-expressing lung cancer cells." (PMID 36006737, 2022). "In this study, we show that the IL-19/IL-20RB axis mediates a direct osteoclastic stimulus to tumor to enhance the proliferation of disseminated lung cancer cells in bone and that IL-20RB can be targeted to treat lung cancer bone metastasis." (PMID 36006737, 2022). "Together, these data demonstrate that JAK1/STAT3 signaling is activated in IL20RB-expressing lung cancer cells by osteoclast-secreted IL-19." (PMID 36006737, 2022). "Furthermore, inhibiting IL-20RB with a neutralizing antibody significantly attenuated lung cancer BM." (PMID 39512767, 2024). "Importantly, blocking IL-20RB with neutralizing antibodies can significantly inhibit lung cancer bone metastasis." (PMID 38571500, 2024). "An IL20RB-neutralizing antibody effectively suppresses bone metastasis of lung cancer." (PMID 36006737, 2022). "Furthermore, immunostaining showed that the expression of IL-20RB in bone metastases of lung cancer was significantly higher than in primary lung tumors, which was also observed in paired bone metastases and primary tumors of the same patients." (PMID 36006737, 2022). "Importantly, immunostaining of clinical bone metastases of lung cancer showed abundant expression of IL-20RB in tumor cells and IL-19 in microenvironmental cells." (PMID 36006737, 2022). "Importantly, blocking IL-20RB with a neutralizing antibody significantly suppressed bone metastasis of lung cancer." (PMID 36006737, 2022). "Furthermore, immunostaining of clinical samples from the SHTCH lung cancer cohort also revealed a strong positive correlation between IL-20RB expression and STAT3 phosphorylation." (PMID 36006737, 2022). "In addition, it is still unknown whether the effect of the IL-19/IL-20RB/STAT3 axis is specific to lung cancer or also applies to other cancer types, such as breast cancer." (PMID 36006737, 2022). "Importantly, FOXP2 knockdown by shRNAs led to suppression of IL20RB in HBM1, indicating that IL20RB might be regulated by FOXP2 in lung cancer." (PMID 36006737, 2022). "Then, the clinical relevance of IL20RB was further validated in a Shanghai Tenth People’s Hospital and Shanghai Chest Hospital (SHTCH) lung cancer cohort." (PMID 36006737, 2022). "In this study, we revealed that ectopic expression of miR-19a or miR-19b-1 modulated the expression of IL-related genes (including IL1B, IL11RA, IL20RB, IL6 and IL32) and suppressed IL6 production in lung cancer and NPC cells." (PMID 32308549, 2020). "For other IRGs, such as LGR4, GDF10, GREM1, IL20RB, INHA, VIPR1, and ADM2, they had been verified to participate in carcinogenesis and affect patients’ prognoses in other cancers, although the relevant studies were rare in lung cancer." (PMID 33386920, 2021).
lung carcinoma (continued). "Furthermore, in vivo and in vitro studies have discovered that lung adenocarcinoma A549 cells induce OCs to secrete the ligand IL-19 for IL-20RB, activating the downstream JAK1/STAT3 signaling pathway, and promoting lung cancer proliferation in the bone microenvironment." (PMID 38571500, 2024).
clear cell renal cell carcinoma (7 papers, 2022 to 2026). "Previous studies have associated IL20RB overexpression with poor prognosis in pancreatic, lung and clear cell renal cell carcinomas; however, its role in CRC has remained largely unexplored." (PMID 41562081, 2025). "IL20RB has been proposed as a prognostic and therapeutic biomarker in clear cell renal cell carcinoma." (PMID 35874683, 2022). "Above all, IL20RB is identified as a novel prognostic and therapeutic biomarker in clear cell renal cell carcinoma from a bioinformatic perspective." (PMID 35299868, 2022). "In addition, IL20RB, interleukin 20 receptor subunit beta, has been found to play an important role in clear cell renal cell carcinoma, while its role in reproduction remains unclear." (PMID 37854191, 2023).
pancreatic cancer (7 papers, 2020 to 2024). "Here, we examined the correlation between IL20RB expression and clinical characteristics of pancreatic cancer, and explored the underlying mechanisms of how IL20RB modulates pancreatic cancer stemness and chemotherapy resistance." (PMID 38098005, 2023). "Previous studies have demonstrated that IL20RB was associated with the prognosis of various cancers, such as lung adenocarcinoma, pancreatic ductal adenocarcinoma, and pancreatic cancer." (PMID 35748788, 2022). "Together, these results suggested that IL20RB promotes the stemness and chemoresistance of pancreatic cancer cells in vivo." (PMID 38098005, 2023). "Subsequently, we performed immunofluorescence analysis for the human pancreatic cancer tissues and found that the expression of IL20RB was positively correlated with the expression of NANOG and SOX2." (PMID 38098005, 2023). "The in vivo studies further confirmed that IL20RB enhanced the tumorigenic ability of pancreatic cancer cells." (PMID 38098005, 2023). "Pancreatic cancer cell lines with Interleukin-20 receptor subunit beta (IL20RB) overexpression and knockdown were established, and clonal formation, spheroid formation and side population cell analysis were conducted." (PMID 38098005, 2023). "The effects of IL20RB knockdown on the tumor-forming ability of pancreatic cancer cells and chemotherapy resistance in vivo were explored." (PMID 38098005, 2023). "In conclusion, the present study is a pioneering work probing into the role of IL20RB in pancreatic cancer." (PMID 38098005, 2023). "We also found that IL20RB overexpression in pancreatic cancer cells increased the number of spheroids, the proportion of SP cells and the expression of stemness markers, indicating that IL20RB resulted in stronger stemness." (PMID 38098005, 2023). "The Cancer Genome Atlas (TCGA) database showed that IL20RB was highly expressed in multiple cancer types, including pancreatic cancer." (PMID 38098005, 2023). "The spheroid formation experiment showed that pancreatic cancer cells with IL20RB overexpression had significantly more spheroids than the control group, while cells with IL20RB knockdown had significantly fewer spheroids." (PMID 38098005, 2023). "Another publicly available transcriptome dataset GSE15471 also confirmed higher expression of IL20RB in pancreatic cancer than in paired normal tissues." (PMID 38098005, 2023). "IL20RB expression was significantly upregulated in pancreatic cancer tissues, and was correlated with unfavorable prognosis." (PMID 38098005, 2023). "Western blot experiments verified that the phosphorylation level of STAT3 was upregulated in pancreatic cancer cells overexpressing IL20RB and was downregulated in those with IL20RB knockdown." (PMID 38098005, 2023). "Mechanistically, IL20RB enhances the stemness and chemoresistance of pancreatic cancer by promoting STAT3 phosphorylation, an effect that can be counteracted by a STAT3 phosphorylation inhibitors." (PMID 38098005, 2023). "In current study, we found that IL20RB was also potentially involved in metastasis progression in pancreatic cancer and other cancers based on the analysis in HCMDB." (PMID 37553583, 2023). "Our findings demonstrate that IL20RB plays a crucial role in promoting stemness in pancreatic cancer." (PMID 38098005, 2023). "We also evaluated the effect of IL20RB knockdown in mouse models, and the results suggested that IL20RB can be a promising therapeutic target for pancreatic cancer." (PMID 38098005, 2023). "Here, we found that IL20RB overexpression enhanced the resistance of pancreatic cancer cells to gemcitabine, whereas IL20RB knockdown had the opposite effect." (PMID 38098005, 2023). "Immunofluorescence staining of the human pancreatic cancer tissues revealed that IL20RB and p-STAT3 were co-expressed in pancreatic cancer cells." (PMID 38098005, 2023). "In this study, we found that IL20RB was highly expressed in pancreatic cancer samples and correlated with poor prognosis." (PMID 38098005, 2023).
pancreatic cancer (continued). "Thirdly, this study lacks therapeutic experiments targeting IL20RB, and the effectiveness of pancreatic cancer therapies targeting IL20RB requires verification." (PMID 38098005, 2023). "IL20RB was found to be highly expressed in pancreatic cancer and enhanced the stemness properties of pancreatic cancer cells and confer resistance to chemotherapy." (PMID 38098005, 2023). "Collectively, these results suggested that IL20RB promotes the stemness of pancreatic cancer cells." (PMID 38098005, 2023). "In addition, high expression of IL20RB in pancreatic cancer tissues was correlated with late tumor stage, late lymph nodes stage, late American Joint Committee on Cancer (AJCC) stage, as well as patient death." (PMID 38098005, 2023). "Notably, microenvironment-derived IL-19 serves as the primary ligand initiating the signaling cascade mediated by IL20RB in pancreatic cancer." (PMID 38098005, 2023). "In the present paper, we found a positive correlation between the protein expression of stemness markers (NANOG and SOX2) and IL20RB in pancreatic cancer samples, suggesting that IL20RB may promote tumor stemness." (PMID 38098005, 2023). "Interestingly, overexpression of IL20RB also promoted the invasiveness of pancreatic cancer compared with control cells in vitro, whereas knockdown of IL20RB had the opposite effect." (PMID 38098005, 2023). "In order to explore the potential of IL20RB in enhancing the stemness of pancreatic cancer cells, we constructed stable cell lines, including MIA PaCa-2 with IL20RB overexpression and PANC-1 with IL20RB knockdown." (PMID 38098005, 2023). "According to the previous study, FYN, LRSAM1, and SEMA6C serve as poor prognostic biomarkers in pancreatic cancer, whereas ERAP2, MET, IL20RB, and CXCL11 indicate improvements." (PMID 36428747, 2022). "In addition, the co-expression of IL20RB and PSTAT3 was observed in clinical pancreatic cancer samples." (PMID 38098005, 2023). "We found that IL20RB is highly expressed in pancreatic cancer through a previous study by our group, not published online, but the role of IL20RB in pancreatic cancer and whether it promotes pancreatic cancer stemness are unknown." (PMID 38098005, 2023). "Notably, treating pancreatic cancer cells with Stattic, a STAT3 inhibitor, substantially reversed the upregulation of mRNA expression of tumor stemness markers (NANOG, SOX2 and POU5F1) induced by IL20RB overexpression." (PMID 38098005, 2023).
renal cell carcinoma (6 papers, 2020 to 2022). "The results revealed that low expression of IL20RB was closely associated with Wnt, mTOR signaling pathway, fatty acid metabolism, and renal cell carcinoma." (PMID 32315986, 2020). "Overexpression of IL20RB has been correlated with cell invasion and migration enhancement, cell proliferation, and poor prognosis in renal cell carcinoma." (PMID 34298727, 2021). "The immune-related genes BIRC5, INHBE, and IL20RB were upregulated in a TMBhigh group and were associated with a poor prognosis, and a combination of PD-1 and CTLA-4 blockers was suggested for the treatment of advanced renal cell carcinoma with aberrations." (PMID 34795663, 2021). "IL20RB is the member of IL10 family, and it was considered crucial in autoimmune diseases and renal cell carcinoma." (PMID 34122500, 2021). "Interestingly, FYN, LRSAM1, IL20RB, CXCL11, S100A1, and MAP3K14 are also well-recognized biomarkers in the prognosis of renal cancer, which is reminiscent of the pancreatic metastasis from renal cell carcinoma in some earlier studies." (PMID 36428747, 2022).
breast cancer (5 papers, 2021 to 2025). A primary or metastatic malignant neoplasm involving the breast. "Next, we generated the Il20rb–/– PyMt mammary tumor cell line using CRISPR/Cas9 gene editing technology." (PMID 39782693, 2025). "WT or Il20rb–/– PyMt mammary tumors were implanted in WT mice and treated with 20 nmol calcipotriol topically every 2 days, starting at 2 days after tumor cell implantation." (PMID 39782693, 2025). "Il20rb–/– PyMt mammary tumor cells showed a similar proliferation rate to WT PyMt cells in vitro." (PMID 39782693, 2025). "As IL20RB is a functional partner of IL20RA, its effects on the stemness properties of breast cancer cells were also investigated." (PMID 33456560, 2021).
lung adenocarcinoma (5 papers, 2019 to 2024). A carcinoma that arises from the lung and is characterized by the presence of malignant glandular epithelial cells. "Considering the role of IL20RB in promoting bone metastasis in lung adenocarcinoma, we selected this gene for further validation." (PMID 39737401, 2024). "In addition, the prognostic value of IL20RB has been actively discussed in multiple tumors including glaucoma, anal cancer, and lung adenocarcinoma." (PMID 33343640, 2020).
papillary renal cell carcinoma (4 papers, 2021 to 2023). A rare subtype of renal cell carcinoma, arising from the renal tubular epithelium and showing a papillary growth pattern, which typically manifests with hematuria, flank pain, palpable abdominal mass or nonspecific symptoms, such as fatigue, weight loss or fever. "IL20RB overexpression can promote cell proliferation, invasion and migration of papillary renal cell carcinoma." (PMID 36544490, 2022). "Overexpression of IL20RB was correlated with poor outcome in patients with papillary renal cell carcinoma, the ability of papillary renal cell carcinoma cells to invade and metastasize could be inhibited by silencing IL20RB in vivo." (PMID 34143198, 2021). "Previous studies have shown that IL20RB is involved in promoting oncogenic functions in papillary renal cell carcinoma, while a retrospective meta-analysis on 466 PDAC patients demonstrated the prognostic value of IL20RB, but the detailed function of IL20RB in PDAC progression remains unknown." (PMID 37553583, 2023).
psoriasis (4 papers, 2018 to 2024). An autoimmune condition characterized by red, well-delineated plaques with silvery scales that are usually on the extensor surfaces and scalp. "IL20RB was found to be associated with inflammatory processes in psoriasis and vitiligo." (PMID 36553569, 2022). "IL-20 is a cytokine belonging to the IL-10 family and its receptor IL-20RB was found to be significantly up-regulated in inflammatory diseases, such as psoriasis and rheumatoid arthritis, indicating its involvement in promoting innate immune responses." (PMID 39519164, 2024).
colitis (3 papers, 2021 to 2024). Inflammation of the colon. "Previous reports have demonstrated that the epithelial cell expression of IL-20RB and IL-20 protein are increased in colitis." (PMID 36613621, 2022). "However, after induction of colitis the symptoms were significantly milder on several days and also cumulatively in the Il20rb KO group compared to WT mice." (PMID 34078403, 2021). "The disease activity index of colitis was less severe in DSS treated Il20rb KO compared to WT mice." (PMID 34078403, 2021). "Moreover, our in vivo experiments demonstrated that activation of IL-20RB significantly influence the severity of colitis." (PMID 34078403, 2021). "However, the symptoms of colitis were significantly milder in Il20rb KO mice suggesting that activity of cytokines of IL-20 subfamily may worsen the symptoms of colitis." (PMID 34078403, 2021).